EPAS1 (endothelial PAS domain protein 1)
Diseases named in the same sentence as EPAS1 in open-access papers (continued):
Sharing a sentence is not in itself a finding about the gene and the disease.
tumor (998 papers, 2001 to 2026). "This case illustrates the predisposition of patients with SCD to PPGLs due to somatic EPAS1 mutations, and should increase awareness of such tumours in these patients." (PMID 41945626, 2026). "The GNAS p.(Arg844Cys) mutation, as well as variants of uncertain significance AKAP13 p.(His641Pro) and EPAS1 p.(Ser478del) were detected in the tumor." (PMID 40175770, 2025). "It is also interesting to investigate the effects of aging and Epas1 deficiency on anti-tumor responses of CD4 T cells." (PMID 39925817, 2025). "We hope to raise awareness of the critical role of the EPAS-1 gene in tumor behavior, risk of disease progression, and recurrence in patients harboring similar phenotypes and carrying these mutations either somatic and/or germline." (PMID 39050329, 2024). "Two tumours had somatic EPAS1 (HIF-2α) pathogenic variants near codon 531 (prolyl) targeted by PHD2." (PMID 38978571, 2024). "Cluster 1B tumors bear PVs in the von Hippel–Lindau (VHL) tumor suppressor gene, HIF-2α encoding gene HIF2α/EPAS1, or the Egl-9 prolyl hydroxylase-1 and -2 encoding gene (EGLN 1/2 encoding PHD 1/2)." (PMID 37958373, 2023). "The increased level of aDCs in low-EPAS1 expression group (AML-patient group) appears to compensate for the tumor immune dysfunction caused by macrophage depletion to some extent." (PMID 37124944, 2023). "It is interesting to note that whole exome sequencing (WES) analyses on both blood and tumor samples revealed a novel EPAS1 mutation, specifically the c.2501A > G; p.Tyr834Cys variant, which has never been reported." (PMID 37576964, 2023). "In the sections above, we emphasized the overrepresentation of hypoxia-related genes in mutated PPGLs (VHL, SDH subunits, EGLN1/2, FH, IDH, EPAS1), highlighting the relevance of this pathway for tumor development." (PMID 34572828, 2021). "The statistical relationship between amplified DNA number and higher mRNA expression of EPAS1 in patients with CRC in this study implied that the hypoxic tumour niches caused molecular changes in EPAS1." (PMID 34250767, 2021). "Relationship between EPAS1 mutations and higher tumour grade indicates that mutations in the EPAS1 sequence contributed to the biological aggressiveness in CRC." (PMID 34250767, 2021). "For example, the expression of EPAS1 protein is inversely associated with the higher grade of tumours." (PMID 34250767, 2021). "In contrast, Imamura and colleagues noted that the loss of EPAS1 expression was strongly associated with advanced tumour stage along with increased vascular endothelial growth factor (VEGF) expression and increased in vitro angiogenesis." (PMID 34250767, 2021). "The association of EPAS1 DNA number amplification or deletion with tumor site and tumor stages indicated the heterogeneous nature of ESCC." (PMID 33042797, 2020). "Identification of the EPAS1 gain-of-function mutation in the resected tumor tissues and circulating leukocytes confirmed the underlying syndrome." (PMID 31185588, 2019). "We next examined the impact of Epas1 deficiency on in vivo anti-tumor activity of CD8 T cells." (PMID 39925817, 2025). "Furthermore, we show that Epas1 expression is significantly reduced in aged CD8 T cells, and loss of Epas1 impairs anti-tumor responses of young CD8 T cells in ACT." (PMID 39925817, 2025). "Our results suggest a possible regulatory mechanism of the tumor immune microenvironment associated with low-EPAS1 expression in AML, which may be helpful to the development of immunotherapy for AML patients in the future." (PMID 37124944, 2023). "While there is a slightly higher tumor mutational burden in EPAS1-altered tumors (9.9 vs. 4.9 mut/Mb), they are enriched in and associated with genes promoting immune evasion, including ARID5B, SPINT1, AAK1, CLIC3, SORT1, SASH1, and FGFR3, respectively (q < 0.001)." (PMID 36421334, 2022).
tumor (continued). "In PCCs/PGLs, the increased stabilization of the HIF2α isoform, encoded by the endothelial PAS domain-containing protein 1 (EPAS1) gene, has been reported to be associated with rapid tumor progression and worse prognosis, thus presenting itself as a promising target for future treatment approaches." (PMID 33494435, 2021). "In addition, the majority (5/8) of tumours with EPAS1 mutations showed higher expression of protein when compared with non-neoplastic adrenal gland or mutation-negative tissues." (PMID 33114456, 2020). "These alterations of EPAS1 were associated with tumor location and T stages." (PMID 33042797, 2020). "The association of EPAS1 mutations with high tumour weight (p = 0.001) and larger tumour size (p = 0.044) implied that mutations of EPAS1 may contribute to the progression of this group of tumours." (PMID 33114456, 2020). "In support of this concept, PGLs carrying somatic EPAS1 (HIF2α) mutations are associated with mosaicism and identical mutations in multiple tumor sites, consistent with the timing of tumor development as a result of postzygotic mutations during early embryogenesis." (PMID 32158431, 2020). "FOXF1 and EPAS1 are both TFs that have been associated with tumor malignancy." (PMID 31106044, 2019). "Furthermore, in the Versteeg dataset, high mRNA levels of HIF1A and EPAS1 were still significantly associated with lower overall survival and relapse-free survival in the sub-set of patients with advanced-stage tumor (i.e., stage 4)." (PMID 26057707, 2015). "The molecular phenotype of EPAS1 mutated tumours has been disputed." (PMID 24466223, 2014). "In particular, somatic EPAS1 variants in SDHB-mutant tumours may have translational relevance." (PMID 38978571, 2024). "Somatic EPAS1 mutations in different cancers indicate that these mutations may occur in a cell during embryogenesis or later, which in turn predispose the affected tissues or organ to form tumours." (PMID 33114456, 2020). "In addition, these alterations of EPAS1 were associated with tumour weight and location." (PMID 33114456, 2020). "In addition, the association of EPAS1 DNA number changes and mRNA expression with clinical and pathological factors, including tumour weight, size, location and the type of tumour, denotes the potential clinical significance of EPAS1 in predicting disease progression." (PMID 33114456, 2020). "Nuclear and cytoplasmic HIF1A and EPAS1/HIF2A expression were assessed by immunohistochemistry in tumours from 40 patients and correlated with clinicopathological parameters and cancer-specific survival." (PMID 42074150, 2026). "In contrast, Epas1 is required for anti-tumor responses of adoptively transferred tumor-specific CD8 T cells, as we demonstrated, but not for anti-tumor responses of endogenous CD8 T cells." (PMID 39925817, 2025). "In contrast, retroviral expression of Epas1 promotes anti-tumor activity of aged CD8 T cells in ACT." (PMID 39925817, 2025). "To understand how Epas1 promotes the anti-tumor response of CD8 T cells, we performed bulk RNA-seq analysis of tumor-infiltrating OT-I T cells treated with Epas1-Crispr." (PMID 39925817, 2025). "We found that both aging and Epas1 deficiency impair accumulation of TCR-T cells in tumors, which likely causes the decreased anti-tumor activity of these cells." (PMID 39925817, 2025). "ZIC5 promotes tumor progression through metabolic pathways, possibly inhibiting EPAS1 activity or competing for the regulation of glycolytic genes." (PMID 40366858, 2025). "To address this, we first investigated the effect of Epas1 deficiency on CD8 T cell activation and cytotoxicity on target tumor cells in vitro." (PMID 39925817, 2025). "In small-cell lung cancer (SCLC), miR-184 was shown to suppress tumour progression through the regulation of endothelial PAS domain protein 1 (EPAS1) and β-catenin, leading to decreased metastatic potential." (PMID 41379397, 2025).
tumor (continued). "Our findings revealed that EZH2, AURKA, BID, PLA2G6, and EPAS1 exhibited significantly elevated expression levels in ccRCC tumor tissues compared to normal tissues." (PMID 40271062, 2025). "The combination groups exhibited a significant decrease in the MKI67-positive cells, the tumor vessel area, and the EPAS1 expression." (PMID 39477683, 2025). "As the tumor progresses to late stages, chronic hypoxia causes a gradual transition from HIF1A to EPAS1/HIF-2α dominance." (PMID 40851276, 2025). "In 10 of these 29 patients, somatic mutations were detected: six tumours with a somatic mutation in the NF1-gene, and two patients each with mutations in the EPAS1- and the VHL-gene." (PMID 41276740, 2025). "Taken together, these results suggest that decreased expression of Epas1 impairs anti-tumor activity of CD8 TCR-T cells in ACT, which can be improved by expression of exogenous Epas1." (PMID 39925817, 2025). "Hypoxia metabolism and (Tumor mutation burden) TMB have a modest correlation, while VWF and EPAS1 are negatively correlated with TMB significantly." (PMID 39901877, 2025). "Suppression of tumor growth was less significant in mice transferred with OT-I T cells treated with Epas1-Crispr compared to controls." (PMID 39925817, 2025). "Flow cytometry analysis revealed that the frequency of Epas1-Crispr-treated OT-I T cells in tumor-infiltrating lymphocytes was significantly lower than in controls." (PMID 39925817, 2025). "Aged CD8 T cells have reduced expression of Epas1, which promotes anti-tumor CD8 T cell responses by enhancing intra-tumoral accumulation of Tpex cells." (PMID 39925817, 2025). "We next sought to explore the possibility that reduction of Epas1 expression is involved in impaired anti-tumor responses of aged CD8 TCR-T cells." (PMID 39925817, 2025). "EPAS1 is an important hub protein in tumor development and still has research value for anti-tumor targeted therapies." (PMID 38612943, 2024). "Studies have shown that the imbalance of EPAS1 expression is related to various tumours such as rectal cancer, pheochromocytoma, neuroblastoma, renal cancer and non‐small‐cell lung cancer." (PMID 38722283, 2024). "The level of EPAS1 expression was low in tumour tissues using the TCGA database, TCGA paired database, GSE113513, GSE32323, GSE21510, GSE8671 and in in‐house database." (PMID 37994607, 2024). "The correlation between macrophages and EPAS1 expression was strongest among the 24 tumor-infiltrating immunocytes (Spearman r = 0.373, P value < 0.001)." (PMID 37124944, 2023). "We further investigated mRNA expression in correlation to tumor subtype and found that EPAS1 levels were higher in sPGLs as compared to PCCs, in line with protein data." (PMID 37463949, 2023). "EPAS1 plays an important role in the development and progression of multiple tumor types by interacting with a series of other molecules." (PMID 37124944, 2023). "HIF-1α and hypoxia-related genes, such as EPAS1, are highly expressed in various hypoxic tumor tissues, which play an important role in tumor angiogenesis, metabolism, and immunity." (PMID 37064872, 2023). "First, by exploring HIF-2 mRNA and protein expression among several different cell types, it provides evidence that bladder UC is the most commonly affected tumor type with the highest frequency of HIF-2/EPAS1 overexpression." (PMID 36421334, 2022). "EPAS1 was downregulated in tumor tissues relative to normal tissues, with significant differences between stages I and III, and II and III." (PMID 36324584, 2022). "The results revealed that when the prognostic indicator was OS, high grade residual tumor, metastasis, positive margin status, high expression of HELLS and STMN1, low expression of EPAS1, CXCL2, NQO1, IL6 were associated with poor prognosis." (PMID 34982796, 2022). "Accordingly, suppression of EPAS1 induced enhanced anchorage‐independent tumour growth in vitro and tumour formation in vivo in xenotransplant mouse." (PMID 34250767, 2021).
tumor (continued). "Studies on genetic to clinical, functional to molecular aspects have given important information regarding EPAS1‐mediated tumour endorsement in CRC pathogenesis." (PMID 34250767, 2021). "Due to the oncogenic effect of EPAS1 in cancerogenesis, EPAS1 is a potential therapeutic target for tumor suppression." (PMID 34828399, 2021). "The trends of EPAS1 copy number amplification were related to larger tumour size, presence of tumour perforation and occurrence of synchronous CRCs." (PMID 34250767, 2021). "In the present study, a trend of association of EPAS1 DNA amplification with larger tumour, the presence of perforation and higher incidence synchronous tumours are in keeping with cancer‐promoting function of EPAS1 in CRC." (PMID 34250767, 2021). "More perceivably, 78% (n = 28/38) of patients having larger tumour (larger than 40 mm in diameter) showed amplified EPAS1 DNA when compared to those of 54% (n = 24/44) of the patient bearing smaller tumour (40 mm or smaller in diameter)." (PMID 34250767, 2021). "Activation of EPAS1 expression plays a central role in driving aggressive tumor phenotypes such as proliferation, angiogenesis, metastasis, and differentiation." (PMID 33088284, 2020). "We observed that EPAS1 DNA amplification significantly (p < 0.05) correlated with the tumor site and pathological stages in patients with ESCC." (PMID 33042797, 2020). "Changes of EPAS1 mRNA expressions were correlated with tumour location and the metastasizing potential of the tumours." (PMID 33114456, 2020). "70.2% (40/57) copy number amplified tumour samples had higher EPAS1 mRNA expression, whereas EPAS1 mRNA downregulation was only noted in 71.5% (5/7) of the EPAS1 DNA number deletion tumours." (PMID 33114456, 2020). "In contrast, miR-184 has demonstrated downregulation in SCLC and acts as a tumor suppressive miRNA as it represses endothelial PAS domain protein 1 (EPAS1)/HIF-2α leading to β-catenin activation." (PMID 32316322, 2020). "On the other hand, most of the tumour samples with EPAS1 copy number amplifications had increased mRNA and protein expression." (PMID 33114456, 2020). "Our MR discovery analysis of human PPGL tumors inferred EPAS1 perturbation in both SDH-loss and VHL-loss tumors, but the overall contribution to tumorigenic transcriptional patterns in both tumor types is underwhelming." (PMID 31234811, 2019). "EPAS1 activation, ultimately, mediates the cellular response to hypoxia and regulates target genes critical for tumor progression, such as VEGFA (angiogenesis) and GLUT1 (metabolism)." (PMID 30614188, 2019). "When validating these potential targets in patients samples, we found that three targets named CSRNP1, MEF2D and EPAS1 are significantly up-regulated in tumor tissues when compared with normal tissues." (PMID 30696880, 2019). "We observed that the tumor volumes and tumor weights in the xenografted mice transplanted with sh‐EPAS1‐transduced OVCAR‐3 S cells were both significantly reduced compared with those in sh‐NC xenografted mice." (PMID 30536571, 2019). "Results showed that CSRNP1, MEF2D and EPAS1 are significantly up-regulated in tumor tissues compared with normal tissues." (PMID 30696880, 2019). "In our evaluation of 13 transcriptomic studies, the inferred activity of EPAS1 was consistently repressed in tumor tissues compared to unaffected lung." (PMID 31503425, 2019). "Additional tests are necessary in the future to determine what factors are required to trigger tumor development in the Epas1 gain-of-function mouse model." (PMID 31091718, 2019). "The developmental role of Epas1 and its regulation by signaling cascades of neurulation provide a probable mechanistic rationale for the long duration of tumor development." (PMID 31091718, 2019). "Three mammalian α subunit isoforms are known, of which HIF-1α and EPAS1/HIF-2α are known to be related to tumor proliferation and progression." (PMID 28060746, 2017).
tumor (continued). "In human NSCLC, overexpression of HIF-2α (EPAS1) was consistently associated with histology as SCC being dominant, increased tumor size, and angiogenesis, resulting in worse prognosis and decreased survival rates." (PMID 26263511, 2015). "It revealed that, together with average tumor size, presence of symptoms, and expression of EPAS1, 2-fold increase in the expression of TMEM72 and TMEM116 decreased the odds of metastases significantly for 22 % and 40 %, respectively." (PMID 26169495, 2015). "The present study validated an amplicon based next generation sequencing method for diagnostic re-sequencing of 11 genes (including EPAS1 and NF1) associated with PCC and PGL tumours." (PMID 26230854, 2015). "The resultant upregulation of hypoxia inducible factors (HIF1α and HIF2α, also known as HIF1A and EPAS1) due to failure of ubiquitination by the mutated VHL leads to vast neovasculature, which subsequently promotes tumour growth." (PMID 25853938, 2015). "Endothelial PAS domain protein 1 (EPAS1), otherwise known as hypoxia-inducible factor 2α has been shown to play a key role in tumor responsiveness to chemotherapy." (PMID 22829886, 2012). "Moreover, combining cc-885 with an EPAS1 inhibitor, belzutifan, significantly enhanced the anti-tumor efficacy." (PMID 42089431, 2026). "Conversely, retroviral expression of Epas1 enhances anti-tumor activity of aged CD8 TCR-T cells." (PMID 39925817, 2025). "Epas1 might also promote infiltration of tumor-specific T cells into tumors, like Hif1a, since Epas1 controls expression of genes involved in tumor infiltration of immune cells, such as Plk4 and Tstd2." (PMID 39925817, 2025). "Importantly, Epas1 deficiency restricts the capacity of young CD8 T cells to accumulate as Tpex-like cells in tumors, so as to control tumor growth." (PMID 39925817, 2025). "There are reports indicating that EPAS1 may support proliferation and migration and increase tumor cell invasiveness." (PMID 40724805, 2025). "Additionally, Epas1-Crispr treatment significantly increased expression of Tim3 in tumor-infiltrating OT-I T cells." (PMID 39925817, 2025). "In addition, our co-regulated subnetwork for MES tumors confirmed the established role of the hypoxic tumor microenvironment, as suggested by the inclusion of EPAS1 and CEBPD, both master TFs for hypoxia-regulated genes in GBM46,47." (PMID 40234567, 2025). "Multiple studies reported that HIF1A may function as a tumor suppressor gene, whereas EPAS1 acts as an oncogene." (PMID 39477683, 2025). "A previous study reported that overexpression of Epas1 promotes anti-tumor CD8 T cell responses, but the role of endogenous Epas1 in CD8 T cells remains unknown." (PMID 39925817, 2025). "To investigate how mTORC2 may regulate SELPLG/PSGL-1 expression in tumor cells, we found that MLST8-KO cells exhibited a significant decrease in expression of EPAS1, the gene encoding HIF2α which was previously shown to be regulated by mTORC2." (PMID 40640525, 2025). "Notably, adoptive transfer of aged OT-I TCR-T cells with Epas1 transduction significantly inhibited tumor growth compared to that of control cells." (PMID 39925817, 2025). "Moreover, EPAS1/HIF-2α has also been demonstrated to regulate or take part in many tumor-related pathways, such as the VEGF and PI3K-Akt pathways." (PMID 38612943, 2024). "EPAS1 in turn enhanced survival under hypoxic conditions which thus may support dendritic tumor cells residing in hypoxic skin lesions." (PMID 38474011, 2024). "ALCL and BPDCN tumor cells are mostly located in (hypoxic) skin lesions where EPAS1 may support their survival." (PMID 38474011, 2024). "Moreover, according to in silico analysis and tissues immunohistochemical analysis, all genes except for EPAS1 were overexpressed in tumor tissues relative to healthy tissues." (PMID 36324584, 2022). "However, while hypoxia is generally associated with poor prognosis, the prognostic role of HIF1A and EPAS1 differs between tumor types." (PMID 36230822, 2022).